HARS1 (histidyl-tRNA synthetase 1)
Description:
Catalyzes the ATP-dependent ligation of histidine to the 3'-end of its cognate tRNA, via the formation of an aminoacyl-adenylate intermediate (His-AMP). Plays a role in axon guidance.
Synonyms: HisRS; HARS; HRS; CMT2W; USH3B
Tractability: Small molecule: a structure with a bound ligand is known. PROTAC: ubiquitination databases record sites on it; a small molecule that binds it is known.
Target class: Enzyme; Ligase
Gene: Protein-coding gene on chromosome 5 (140,673,035 to 140,691,537, reverse strand). Ensembl gene ENSG00000170445.
Subcellular location: Cytoplasm
Subcellular location (Human Protein Atlas): Cytosol
Pathways (Reactome):
Metabolism of proteins: Cytosolic tRNA aminoacylation
Gene Ontology:
Molecular function: ATP binding; histidine-tRNA ligase activity; identical protein binding; protein homodimerization activity; RNA binding; aminoacyl-tRNA ligase activity
Biological process: histidyl-tRNA aminoacylation; translation; tRNA aminoacylation for protein translation
Cellular component: cytosol; cytoplasm
Genetic constraint (gnomAD): Loss-of-function variants: 25 observed, 36.49 expected, observed/expected ratio (o/e) 0.69, 90% interval 0.5 to 0.96. The upper end of that interval is the gene's LOEUF score, 0.96, which puts it in group 4 of 6, group 1 being the genes least tolerant of losing a copy. Missense variants: 321 observed, 454.91 expected, observed/expected ratio (o/e) 0.71, 90% interval 0.64 to 0.77. Synonymous variants: 147 observed, 182.6 expected, observed/expected ratio (o/e) 0.81, 90% interval 0.7 to 0.92.
Gene-disease validity (ClinGen):
ClinGen rates the evidence that HARS1 causes each of these diseases.
Usher syndrome type 3 (autosomal recessive): Refuted. A syndrome characterized by postlingual progressive hearing loss, abnormalities in the vestibular system, and onset of retinitis pigmentosa symptoms usually by the second decade of life.
Homologues: Orthologues: chimpanzee HARS1 (99% identical), macaque HARS1 (99% identical), rabbit HARS1 (97% identical), dog HARS1 (96% identical), guinea pig HARS1 (95% identical), mouse Hars1 (95% identical), rat Hars1 (94% identical), pig HARS1 (93% identical), zebrafish hars (73% identical), Drosophila melanogaster HisRS (63% identical), tropical clawed frog hars1 (60% identical), Caenorhabditis elegans hars-1 (55% identical). Paralogues in human: HARS2 (72% identical).
Diseases named in the same sentence as HARS1 in open-access papers:
HARS1 is named in the same sentence as 24 diseases in open-access papers, as found by Europe PMC text mining. Sharing a sentence is not in itself a finding about the gene and the disease. The quoted sentences say what the papers report.
Usher syndrome (7 papers, 2014 to 2025). A syndromic diseae characterized by the association of sensorineural deafness (usually congenital) with retinitis pigmentosa and progressive vision loss. "For carbohydrates, glucose level was significant for an intronic variant (rs11954514) in the HARS1 (Histidyl-tRNA synthetase 1) gene that is a disease-causing gene for Usher syndrome type 3b (MIM ID: 614504)." (PMID 36482414, 2022).
Ataxia (2 papers, 2024). Ataxia refers to impaired coordination of voluntary muscle movement. "On the other hand, the loss of function of DARS, RARS, KARS, HARS1, SARS, and NARS2/PARS2 were reported to cause neurological diseases that share ataxic feature, indicating an important role of ARS function in the pathogenesis of ataxia." (PMID 38869703, 2024).
Charcot-Marie-Tooth (CMT) disease (2 papers, 2023). "The most common condition, the Charcot-Marie-Tooth disease (CMT), is associated with dominant, monoallelic mutations in six aaRSs genes (e.g.,YARS1, MARS1, KARS1, WARS1, AARS1, GARS1, and HARS1)." (PMID 37495112, 2023). "Thus far, autosomal dominant mutations in AARS1, GARS1, HARS1, MARS1, WARS1, SARS1 and YARS1 have been linked to peripheral neuropathies, predominantly Charcot-Marie-Tooth (CMT) disease." (PMID 37274211, 2023).
microcephaly (2 papers, 2021 to 2025). A congenital or acquired developmental disorder in which the circumference of the head is smaller than normal for the person's age and sex. "While recessively inherited ARS1 disorders share some common clinical signs, e.g., involvement of the CNS and microcephaly (in all but HARS1), there is a striking heterogeneity of the clinical manifestation which does not follow a reproducible pattern." (PMID 34536092, 2021).
COVID-19 (1 paper, 2021). A disease caused by infection with severe acute respiratory syndrome coronavirus 2. "The univariate Cox analysis highlighted that 7 genes (including MRC1, CP, ITGA5, SNCA, HARS1, ENPP1, and PLAU) were significantly (p < 0.05) associated with CHOL/COVID-19." (PMID 34176789, 2021). "As per the independent prognostic and survival analyses, few of the important differentially expressed genes, including MRC1, CP, ITGA5, SNCA, HARS1, ENPP1, and PLAU may function as potent biomarkers for screening and characterizing different stages of CHOL patients with COVID-19." (PMID 34176789, 2021).
peripheral neuropathy (5 papers, 2016 to 2025). A disorder affecting the peripheral nervous system. "Loss of function mutations in HARS1 cause peripheral neuropathies that is likely caused by reduced translation efficiency." (PMID 36482414, 2022). "While HARS1 mutations have been implicated in peripheral neuropathy due to impaired protein synthesis and increased cellular stress, its downregulation in DN may suggest a similar mechanism within renal tissues." (PMID 40868959, 2025). "Specifically, mutations in AARS1 have been identified as the likely cause of Swedish-type hereditary diffuse leukoencephalopathy with spheroids 2 (HDLS2 or HDLS-S), and a dominant HARS1 variant has been linked to cerebellar degeneration, cognitive impairments, and peripheral neuropathy." (PMID 37274211, 2023).
infection (1 paper, 2016). The state of being infected such as from the introduction of a foreign agent such as serum, vaccine, antigenic substance or organism. "Quite the contrary, many clones targeting genes required for translation, including those encoding aminoacyl-tRNA synthetases (hars-1, lars-1, rars-1, tars-1, wars-1) and eIF subunits, were required for expression of nlp-29 after infection." (PMID 27129311, 2016).
HARS1 also shares sentences with these, for which no sentence is quoted: breast carcinoma (2 papers); cancer (2); myositis (2); neurological diseases (2); neuropathies (2); Usher syndrome type 3B (2); antisynthetase syndrome (1); deafness (1); distal hereditary motor neuropathy (1); distal motor neuropathy (1); idiopathic inflammatory myopathy (1); Intellectual disability (1); melanoma (1); pancreatic cancer (1); polyneuropathies (1); tumor (1); Usher syndrome type 1G (1).